ITGB5 (integrin subunit beta 5)
Diseases named in the same sentence as ITGB5 in open-access papers (continued):
Sharing a sentence is not in itself a finding about the gene and the disease.
infection (8 papers, 2013 to 2024). The state of being infected such as from the introduction of a foreign agent such as serum, vaccine, antigenic substance or organism. "“PI3K/AKT” and “Integrin signalling” were significant in IPA of the IA-H/S data set and several infection-associated genes involved in integrin signalling, possess differences in the number of TashAT2 binding motifs between the two genomes (LAMC1, ACTA2, ITGA4 and ITGB5)." (PMID 35061738, 2022). "In THP-1-macrophages, we also observed reduced expression of SRA1, ITGB5, and TIM4 receptors in response to infection with SARS-CoV-2." (PMID 35666101, 2022). "Secondly, we assessed the relative effects of ITGB5 and MUC13 on mRNA expression of the two mucin genes (MUC4 and MUC20) in response to 3 h infection with ETEC strain 200 (MOI = 8∶1) at 44 h after siRNAs transfection." (PMID 23922972, 2013). "We have previously found that the expression of porcine MUC13 and MUC4 was down-regulated in IPEC-J2 cells post infection with the same F4ac ETEC strain, and the expression of ITGB5 was not significantly decreased." (PMID 23922972, 2013).
bacterial infection (1 paper, 2012). "The protein type of ITGB5 belongs to the integrin beta chain family, and is associated with alpha-V for compounding integrin αVβ5, which plays an important role in the innate defence system against bacterial infection by influencing the rapid turnover and exfoliation of mucosal epithelial cells." (PMID 22457712, 2012).
kidney disease (1 paper, 2020). "Also, ITGB5 contributes to cell adhesion and known as a biomarker in kidney disease." (PMID 31907669, 2020).
neurodegenerative disease (1 paper, 2025). A disorder of the central nervous system characterized by gradual and progressive loss of neural tissue and neurologic function. "Additionally, ITGB5 expression has been associated with neurodegenerative diseases such as PD, HD, and AD as well." (PMID 40106490, 2025).
ITGB5 also shares sentences with these, for which no sentence is quoted: dementia (2 papers); lung carcinoma (2); age (1); amyloid (1); atherosclerosis (1); basal cell carcinoma (1); bladder cancer (1); Blepharophimosis (1); cholangitis (1); chronic kidney disease (1); Cirrhosis (1); colon cancer (1); colorectal adenocarcinoma (1); dilated cardiomyopathy (1); endometrial adenocarcinoma (1); glaucoma (1); head and neck cancer (1); human papillomavirus infection (1); Hyperglycemia (1); Jaundice (1); lung adenocarcinoma (1); lung squamous cell carcinoma (1); malaria (1); malignant glioma (1); mood disorder (1); mucinous adenocarcinoma (1); myocarditis (1); nasopharyngeal carcinoma (1); pancreatic ductal adenocarcinoma (1); Parkinson disease (1).
A further 6 diseases each share a sentence with ITGB5 in 1 paper.